NTRK3 (neurotrophic receptor tyrosine kinase 3)
Diseases named in the same sentence as NTRK3 in open-access papers (continued):
Sharing a sentence is not in itself a finding about the gene and the disease.
cancer (135 papers, 2011 to 2026). A tumor composed of atypical neoplastic, often pleomorphic cells that invade other tissues. "Scenarios include NTRK fusion genes, such as NTRK1, NTRK2, and NTRK3 (encoding tropomyosin receptor kinases, TrkA, TrkB, and TrkC, respectively), that link the tyrosine kinase domain with a 5’ fusion partner (over 50 partners across cancers)." (PMID 39956859, 2025). "Specifically, NTRK3 mutations were discovered in 229 patients and associated with robust anti-cancer activities in terms of ORR (45.4% vs. 28.3%; P < 0.001), PFS (HR = 0.72; 95% CI, 0.58–0.89; P = 0.01), and OS (HR = 0.60; 95% CI, 0.50–0.73; P < 0.001)." (PMID 38658978, 2024). "NTRK3 expression was associated with worse progression‐free survival, cancer‐specific survival, and overall survival in UTUC tissues." (PMID 38593276, 2024). "Higher NTRK3 expression was associated with worse progression‐free survival, cancer‐specific survival and overall survival in patients with UTUC in this study." (PMID 38593276, 2024). "The gene fusion seen in nearly all of these types of cancer is ETS translocation variant 6 (ETV6)–NTRK3 fusion." (PMID 37212982, 2023). "The fusion variant of ETV6- NTRK3 was noted in 4 out of 17 ETV6 translocation-positive secretory carcinomas, which were defined by FISH assays." (PMID 31822803, 2020). "Dysregulations of NTRK3 signaling are known to be implicated in numerous cancers." (PMID 37658038, 2023). "A screen of NTRK3 mutations in these cancers should open new therapeutic avenues." (PMID 37658038, 2023). "Furthermore, numerous other protein kinases implicated as driver genes in various other cancers were identified here, including NTRK3 and MAP2K7." (PMID 33572851, 2021). "In summary, these findings suggest that NTRK3 mutations affect multiple signaling pathways and may play roles in cancer through these pathways." (PMID 32903385, 2020). "NTRK fusions, which result from rearrangements in the NTRK1, NTRK2, or NTRK3 genes (encoding TRKA, TRKB, and TRKC, respectively), are actionable oncogenic drivers found in a diverse range of adult and pediatric cancers." (PMID 41492362, 2026). "The TRK family, comprising TrkA, TrkB, and TrkC, encoded by NTRK1, NTRK2, and NTRK3, respectively, has emerged as a critical therapeutic target in cancer." (PMID 39860039, 2025). "Despite its role, research on the correlation between NTRK3 and cancer remains limited, necessitating further investigation." (PMID 40142285, 2025). "Differential expression of NTRK3 between tumors and normal tissues has been observed in various cancers, and NTRK3 expression is lower in BC tissues than in normal adjacent tissues." (PMID 40142285, 2025). "In cancer, NTRK3 is often involved in gene fusions, where part of the NTRK3 gene is joined to another gene, leading to the production of a fusion protein that can drive tumorigenesis." (PMID 40142285, 2025). "Higher NTRK3 expression was correlated with worse progression‐free survival, cancer‐specific survival, and overall survival." (PMID 38593276, 2024). "The ANRS consists of five ANRGs: SPIB, CD24, NTRK3, EDA2R, and PLK1, all of which have been extensively linked to cancer." (PMID 39596658, 2024). "Rearrangements involving the neurotrophic-tropomyosin receptor kinase (NTRK) gene family (NTRK1, NTRK2, and NTRK3) have been identified as drivers in a wide variety of human cancers." (PMID 38863624, 2024). "Neurotrophin-3 (NT3) is the only nerve growth factor that particularly binds to TrkC and alterations such as mutations or fusions involving NTRK3 can lead to constitutive activation of TrkC, contributing to oncogenesis in specific cancer contexts." (PMID 39124968, 2024). "Significant correlations were observed between NTRK3 expression and cancer stage (p = 0.009), lymphovascular invasion (p = 0.012), cancer progression (p = 0.003), and cancer death (p = 0.002)." (PMID 38593276, 2024).
cancer (continued). "NTRK fusion-positive cancers, specific mutations in the kinase domain, such as NTRK1 G595R and NTRK3 G623R, have been implicated in resistance by altering TKI binding affinity." (PMID 39518080, 2024). "As in adults, more aggressive cancer behavior is expected in cases harboring p.V600E or other BRAF point mutations or BRAF-like fusions (e.g., RET/PTC1, NTRK3/ETV6, ALK rearrangements), although these correlations remain unconfirmed in children." (PMID 37046700, 2023). "These tyrosine kinase receptors have received some attention from the clinical point of view, given that NTRK gene fusions including NTRK1, NTRK2, and NTRK3 are identified as oncogenic drivers in various types of tumors, including an increase in cancer in DM1." (PMID 36767649, 2023). "Neurotrophic tyrosine receptor kinase 1, 2, and 3 (NTRK1, NTRK2, and NTRK3) genes encode for three tyrosine kinase receptors (TRKA, TRKB, and TRKC, respectively) and act as oncogenic drivers in a well-defined subgroup of cancers." (PMID 37876963, 2023). "Finding BRAF mutations or PPARG, NTRK1, NTRK3 and ALK fusions were strong predictors of a higher risk of cancer (approaching 100%) while other mutations like RAS, PTEN and EIF1AX or THADA fusions were associated with a significant but lower risk of cancer." (PMID 37510219, 2023). "Gene fusions involving NTRK1, NTRK2, and NTRK3 are rare drivers of cancer that can be targeted with histology-agnostic inhibitors." (PMID 35328221, 2022). "Among the three NTRK genes, NTRK1 and NTRK3 gene fusions can be identified in a wide range of cancer types, NTRK3 fusion is the most common followed by NTRK1 fusion, and ETV6-NTRK3 along with TPM3-NTRK1 are the most common fusion partners." (PMID 35372074, 2022). "NTRK1-rearranged carcinomas have been more aggressive with multifocality than NTRK3-rearranged carcinomas." (PMID 35625691, 2022). "Trk aberrations, including gene fusion, gene overexpression, and single nucleotide variation, are involved in the pathogenesis of many cancers, among which NTRK3 gene fusion is extremely confirmed for oncogenic event." (PMID 35141152, 2021). "Using H226 cells, we observed that NTRK3 levels were higher in CSC-enriched sphere cultures relative to predominantly bulk cancer cells maintained in attached culture conditions." (PMID 35006496, 2021). "Among the genes in the ZNF132 node, CBX7 is implicated in cancer progression and EMT, PTPRN2 confers resistance to apoptosis, and NTRK3 is a receptor tyrosine kinase whose overactive kinase domain is implicated in growth and metastasis." (PMID 34797887, 2021). "Neurotropic tropomyosin receptor kinases (NTRK1, NTRK2, and NTRK3) encode tyrosine receptor kinases (TRKA, TRKB, and TRKC), which induce many types of cancer pathogenesis through the activation of downstream signaling." (PMID 35008821, 2021). "Results provide evidence that SLITRK3 gene amplification frequently occurring in LUSC causes aberrant SLITRK3 overexpression and facilitates SLITRK3-dependent ligand activation of NTRK3 to induce a cancer stem cell (CSC) phenotype." (PMID 35006496, 2021). "One such example are gene rearrangements that fuse ETV6 to the tyrosine kinase domain of neurotrophic receptor tyrosine kinase 3 (NTRK3), forming a chimaeric oncoprotein known as EN, which is expressed in various cancers." (PMID 34066106, 2021). "In previous studies, NTRK3 has been demonstrated to be an oncogene or a tumor suppressor gene in different cancer types." (PMID 33593392, 2021). "NTRK1-rearranged carcinomas showed a higher frequency of multifocality and aggressivity than NTRK3-rearranged carcinomas." (PMID 33923728, 2021). "The patients with carcinomas harboring NTRK1 fusions had LN metastases 80% of the time compared to 49% of time for NTRK3 fusion-positive carcinomas." (PMID 33923728, 2021).
cancer (continued). "The predominant follicular pattern was more common in NTRK3 than in NTRK1 fusion-positive carcinomas, in which the follicular architecture mostly co-occurred with foci of papillary formation." (PMID 33923728, 2021). "The carcinomas harboring NTRK3 fusions (n = 49) were compared to the carcinomas with NTRK1 fusions (n = 10)." (PMID 33923728, 2021). "The carcinomas positive for NTRK1 fusions had a significantly more common mixture of papillary and follicular growth patterns (p = 0.006) than the carcinomas positive for NTRK3 fusions, which had mostly predominant follicular growth patterns." (PMID 33923728, 2021). "In most NTRK3 fusion proteins, the 3′ region of NTRK3, which contains the tyrosine kinase domain fused with the 5′ region of the partner gene, is expressed in cancer." (PMID 31936239, 2020). "Accumulating evidence suggests that NTRK3 is crucial to the development of not only the nervous system but also cancer." (PMID 32903385, 2020). "Additional NTRK3 fusion proteins, occurring in small numbers, have been identified in various cancer types." (PMID 31936239, 2020). "While the frequency of NTRK fusions proves to be low in common cancer types, including NSCLC, NTRK3 fusions were revealed to be almost ubiquitous among rare cancer types, such as mammary analog secretory carcinoma and infantile fibrosarcoma." (PMID 31737634, 2019). "Even if in the same cancer in different situations, such as stages, sex, ages and so on, NTRK3 has different roles." (PMID 27351280, 2016). "Both RNA34433 and NTRK3 were predicted to be targeted by has-miR-297, whose potential role in cancer genesis should be further investigated." (PMID 26812883, 2016). "Our studies provide further insight into the complex relationship between NTRK3 and NT-3 in cancers as well as into dependence receptor biology in the colon." (PMID 23874207, 2013). "NTRK3 may be a critical factor in cancer progression, including gastric, thyroid, lung, glial, and BCs." (PMID 40142285, 2025). "A total of 118 UTUC cancer tissue samples were examined to evaluate the expression of NTRK3." (PMID 38593276, 2024). "Similarly, NTRK gene fusions involving NTRK3 (48%) or NTRK1 (39%) were common in patients with TRK fusion cancer prior to enrollment in clinical trials involving larotrectinib." (PMID 38925616, 2024). "Sixty‐four (54.2%) of the cancer samples exhibited high levels of NTRK3 expression." (PMID 38593276, 2024). "NTRK3 promoter methylation could serve as a prognostic marker in multiple cancers, and its prognosis role is different in various cancers." (PMID 33593392, 2021). "In recent years, many studies have reported that TRK pathway aberrations such as single nucleotide variation, gene fusion and gene overexpression are involved in the pathogenesis of many cancers, among which NTRK3 gene fusion is the most fully verified carcinogenic event." (PMID 33894748, 2021). "Altogether, the results indicate that gene amplification and consequent high expression of SLITRK3 in LUSC is associated with worse outcomes and induces SLITRK3-dependent activation of NTRK3 to promote a cancer stem cell phenotype that is inhibited by existing NTRK-targeted inhibitors." (PMID 35006496, 2021). "Furthermore, we revealed that NTRK3 promoter hypermethylation is highly associated with MSI and KRAS mutation that is known as response biomarkers for cancer treatment and have conflicting predictive value for survival." (PMID 33593392, 2021). "This was Central Carbon metabolism in Cancer with three associated genes EGFR, NTRK3, and SLC7A5." (PMID 33317464, 2020). "We also analyzed whether another member of the same family, Ntrk3, can impact KP cancer cell biology in a similar manner as Ntrk1." (PMID 30986992, 2019).
cancer (continued). "Fusions of NTRK1, NTRK2, and NTRK3 and their partner genes can lead to overexpression of Trk proteins, which in turn activate downstream signaling pathways, such as RAS/MAPK, PI3K/AKT, and PLC-γ, causing transformation, proliferation, and survival of cancer cells." (PMID 41383499, 2025). "Therefore, further investigation is needed to fully understand the dual roles of NTRK3 in BC and to identify the specific conditions under which its expression may either inhibit or enhance cancer progression." (PMID 40142285, 2025). "Moreover, NTRK3 plays a pleiotropic role in regulating the pathobiology of many cancers." (PMID 38593276, 2024). "Moreover, the results of an Ingenuity Pathway Analysis suggested that NTRK3 may interact with the PI3K‐AKT‐mTOR signaling pathway to promote cancer." (PMID 38593276, 2024). "Similarly, NTRK3-KHDRBS1 was discovered in an infant with a CD34-positive spindle-cell skin tumor and is of particular interest due to the more recent identification of NTRK3 fusions as drivers in the development of rare cancer types, as well as the recent development of TRK inhibitors." (PMID 33281875, 2020). "Inhibitors such as larotrectinib, entrectinib and repotrectinib are used when cancer cells harbor NTRK1, NTRK2 or NTRK3 fusion." (PMID 41744839, 2026). "The differentially expressed gene (DEG) analysis identified nine genes, including NTRK3 and CTSG, which are known to be involved in TiME in several cancer types." (PMID 39891665, 2025). "Some studies have accounted for predicted and validated gene targets like GATA2, SKI, NTRK3, PAK2, AR, SP1, and CDK4 that describe their involvement in cancer progression." (PMID 38741808, 2024). "We analyzed 8,805 3’ kinase gene fusions curated from the COSMIC, focusing on the seven most common kinase fusions involving ALK, RET, ROS1, NTRK1, NTRK3, ABL1, and BRAF genes found in various types of cancers." (PMID 38877018, 2024). "Addressing this need, the current report introduces the novel cancer gene SLIT- and NTRK-like family member 3 (SLITRK3) and its role in activating the neurotrophic receptor tyrosine kinase 3 (NTRK3) in LUSC cells." (PMID 35006496, 2021). "Chromosomal translocations involving the NTRK1, NTRK2, and NTRK3 genes result in constitutive activation and aberrant expression of TRK kinases in numerous cancer types." (PMID 32466202, 2020). "Oncogenic fusion genes involving the NTRK family (NTRK1, NTRK2, or NTRK3) have been identified in various cancers, and a few NTRK-TKIs have been effective against the NTRK-rearrangement-positive cancers in clinical trials." (PMID 31399568, 2019). "Some of these integration sites interrupt important cancer genes such as CCNE1 (sample 106 T, chr19:30304177) and NTRK3 (sample 108 T, chr15:88688212)." (PMID 30704462, 2019). "MGCD516 (Mirati Therapeutics Inc., San Diego, CA, USA) is another multi-kinase inhibitor in a phase 1/1b clinical trial (NCT02219711) for patients with advanced cancers expressing rearranged MET, RET, AXL, NTRK1, or NTRK3 genes." (PMID 29617282, 2018). "Here, we found fusion genes involving BRAF, NTRK3, ALK, FGFR1, and ROS1, which result in activation of the MEK/ERK pathway in other cancers." (PMID 29654269, 2018). "NTRK3 (also known as TRKC), hypermethylated in 97.76% of the 268 CRC samples, was found to be hypermethylated and downregulated in 15 of the 16 cancer tissues compared with their paired adjacent normal tissues respectively." (PMID 28537885, 2017). "Kinase fusion genes detected across multiple cancer types include RET, NTRK1, NTRK3, ALK, ROS1, FGFR1/2/3, and serine threonine kinases including the RAF family genes BRAF, RAF1, CRAF, and MAST1/2." (PMID 26684754, 2015). "As shown, these miRNAs are active regulators of the expression of several cancer-related mRNAs, including ZEB1, ZEB2, VIM, VEGFA, NTRK3 and SPDEF, and most of the miRNAs are cancer-related." (PMID 24512620, 2014).
cancer (continued). "We also detected several low-frequency, pan-cancer kinase fusion events, for example in the neurotrophic tyrosine receptor kinases NTRK1, NTRK2 and NTRK3, that drive tumorigenesis in a small fraction of multiple cancers, regardless of tissue type." (PMID 25204415, 2014). "The fusion partner of NTRK3 detected in the China Pan-cancer study is not a common partner detected in other adult NTRK3 fusion-positive tumors." (PMID 41516212, 2025). "A direct comparison with the cancer genome atlas (TCGA) adult series cannot be made, but it is worth noting that NTRK3 rearranged PTCs, as well as ALK and NTRK1, were not consistently and homogeneously defined as BRAF-like or RAS-like tumors." (PMID 34206589, 2021). "There are no records of comparison between NTRK1 and NTRK3 fusion-positive carcinomas in the literature." (PMID 33923728, 2021). "In the second study, pan-TRK IHC was less effective in detecting fusions involving NTRK3, which may reduce the overall sensitivity of IHC as the ETV6-NTRK3 fusions has been reported as the most common TRK fusion in pan-cancer studies." (PMID 31256325, 2020). "Two significantly enriched pathways in LUAD and their related DEmRNAs, namely transcriptional misregulation in cancer (TGFBR2, FLI1, ERG and SIX1) and central carbon metabolism (NTRK3 and SLC7A5), were speculated to play key roles in LUAD regulated by DEmiRNAs." (PMID 30761256, 2019). "After enriching the DML (smokers vs. nonsmokers) for cancer-related genes, we found the Trk and Shp2 pathways to be differentially activated between these groups; these differences were driven by hypermethylation of the NTRK2 and NTRK3 genes in smokers." (PMID 27795744, 2016).
adenocarcinoma (6 papers, 2013 to 2024). A common cancer characterized by the presence of malignant glandular cells. "High-grade adenocarcinoma with similar morphology and an ETV6::NTRK3 fusion, arising in the parotid gland of a 22-year-old male patient, was reported recently." (PMID 37415052, 2023). "For the first time, we describe 2 cases of primary high-grade non-intestinal type adenocarcinomas of the nasal cavity, distinct from secretory carcinoma by morphology and immunoprofile, harboring the ETV6::NTRK3 fusion." (PMID 37415052, 2023).
benign tumors (3 papers, 2018 to 2022). "NTRK1 and NTRK3 fusions were indeed more common in the Dutch population (n = 4 and n = 5, respectively), mostly in benign tumors, and all of these patients were tested for the differential diagnosis." (PMID 35328221, 2022). "Of these, 15 proteins (PRSS8, MK, WFDC2 (HE4), IL-10, SOD2, PARP-1, hK11, PVRL4, MUC-16 (CA125), FR-alpha, CDH3, NTRK3, IL-8, IL-17C, EN-RAGE) were selected from the comparison between OC stage I–IV and benign tumors." (PMID 30519148, 2018).
CNS tumors (3 papers, 2022 to 2024). "All gene fusion events identified in this study were in NTRK1or NTRK3, consistent with previous data indicating that fusions in TC very rarely occur in the NTRK2 gene, which is primarily associated with primary CNS tumours." (PMID 35333737, 2022).
hematologic diseases (2 papers, 2013 to 2024). "TEL fusion proteins with other tyrosine kinases, such as ABL1, ABL2, JAK2, NTRK3, FFGR3, and PDGFRB, have also been associated with various hematologic malignancies, though direct comparisons between these fusion proteins in mouse models is not complete." (PMID 24116232, 2013). "Multiple chromosomal rearrangements involving ETV6 (such as ETV6::RUNX1, ETV6::ABL1, ETV6::NTRK3, and ETV6::ACSL6) have been demonstrated to play a crucial role in the development of several hematologic diseases such as AML, as well as in their diagnosis and prognosis." (PMID 39723366, 2024).
neurological disease (2 papers, 2012 to 2025). "Ntrk3, adenylate cyclase activating polypeptide 1 receptor 1 (Adcyap1r1), E2F transcription factor 1 (E2f1) and X-ray repair in Chinese hamster cells 6 (Xrcc6) were represented within the “neurological disease” pathway." (PMID 22934110, 2012).
gastrointestinal tumors (1 paper, 2010). "Of the top 10 genes that were hypermethylated in CIMP-H compared to CIMP-L tumors, 5 have previously been implicated in the pathogenesis of gastrointestinal tumors (NTRK3, HS3ST2, TWIST1, CD40 and EYA4)." (PMID 20492682, 2010).